EGF (epidermal growth factor)
Diseases named in the same sentence as EGF in open-access papers (continued):
Sharing a sentence is not in itself a finding about the gene and the disease.
cancer (continued). "Moreover, due to the loss of Tks4 having similar effects on cancer cells as EGF treatment (EMT induction, reduced E-cadherin expression), it is possible that Tks4 plays a putative negative regulatory role in the EGFR pathway by delaying signal transduction or changing its kinetics." (PMID 31671862, 2019). "EGF signaling has been involved in a myriad of cellular processed such as migration of cancer cells and the invasion of tissues, development of myelin, and differentiation of oligodendrocytes." (PMID 41513629, 2026). "EMT, induced by factors including TGF-β, fibroblast growth factor (FGF), and epidermal growth factor (EGF), contributes to resistance against various cancer therapies." (PMID 41522355, 2026). "This ability enables cancer cells to autonomously drive their own growth, thereby circumventing the requirement for external mitogenic signals such as epidermal growth factor (EGF) and its receptor (EGFR)." (PMID 41602751, 2026). "This matriptase-induced HGF/c-MET signaling constitutes a second wave of EGF signaling, promoting cancer cell scattering, migration, and invasion." (PMID 40361420, 2025). "These interaction network analyses reinforce the distinct and complex roles of CCL18 and EGF in cancer biology, particularly in BRCA." (PMID 40692603, 2025). "These gene sets likely reflect molecular partners or pathways modulated by CCL18 and EGF, encompassing processes such as immune regulation, extracellular matrix remodeling, and cell migration—hallmarks of cancer progression." (PMID 40692603, 2025). "Adding to the complexity of this signaling network, vesicular trafficking also mediates a reciprocal interaction between matriptase and EGF signaling, which contributes to cancer progression." (PMID 40361420, 2025). "The processes of proliferation and survival signaling in cancer cells involve complex interactions among growth factors such as epidermal growth factor (EGF), transforming growth factor (TGF)-α, and TGF-β." (PMID 40572648, 2025). "The fusion proteins, mPA-ZHER2 (mPA fused to a HER2-specific affibody) and mPA-EGF, selectively target HER2-positive and EGF-positive cancer cells." (PMID 41003524, 2025). "To investigate the expression profiles of CCL18 and EGF across multiple cancer types, we performed a comprehensive differential expression analysis using data from TCGA." (PMID 40692603, 2025). "These shape alterations significantly impact measured capacitance values, potentially masking true biological responses to epidermal growth factor (EGF) stimulation that are essential for cancer detection." (PMID 41294763, 2025). "In this study, we explored the anti-cancer effects of EGF-immobilized NPs using PSNPs and polymeric micelles as carrier platforms." (PMID 41140511, 2025). "We found that cancer epithelial cells with elevated SHCBP1 expression exhibited a strong interaction with stromal cells through the EGF, VEGF, IGFBP, CypA, GRN, and PTN signaling pathways." (PMID 40799237, 2025). "The distinctive feature of this vaccine is its ability to interfere with the binding of EGF to its receptor on the surface of cancer cells, preventing their proliferation." (PMID 41303538, 2025). "Several studies have reported the application of polymeric NPs functionalized with EGF- or EGFR-binding peptides to deliver anti-cancer drugs to cancer cells using pilot ligands as targeting molecules." (PMID 41140511, 2025). "Epidermal growth factor (EGF)-immobilized polymeric nanoparticles demonstrated anti-cancer activity in cancer cells that respond poorly to conventional EGF receptor-targeted anti-cancer drugs, indicating promising potential for medical applications." (PMID 41140511, 2025).
cancer (continued). "Cell differentiation is a key process in cancer progression, which is regulated by epidermal growth factor (EGF) among others." (PMID 39936247, 2025). "EGF-immobilized gold nanoparticles (NPs) serve as a new candidate for anti-cancer drugs targeting EGFR." (PMID 41140511, 2025). "Among them, the EGF-EGFR signaling pathway is implicated in cell proliferation, survival, and differentiation, its dysregulation has been linked to various cancers." (PMID 39951434, 2025). "ARL4C is frequently overexpressed in various cancers due to aberrant activation of Wnt–β-catenin and EGF–RAS pathways." (PMID 39833546, 2025). "The effects of EGF on lipid metabolism have been particularly well studied in cancer models, where it primarily promotes fatty acid synthesis." (PMID 39433211, 2025). "Another growth factor, epidermal growth factor (EGF), is also involved in cancer, and thus a peptibody-targeting EGF receptor was developed for cancer treatment." (PMID 41020890, 2025). "EGF and IL-1 were recognized to regulate the expression of genes involved in inflammation and cancer." (PMID 40698360, 2025). "Previous studies indicated that epidermal growth factor (EGF) receptor (EGFR) induces GEFs to activate ARF6 in invasive cancers, which promotes cancer cell migration and invasion." (PMID 40082743, 2025). "It accomplishes this by downregulating essential molecules involved in various signaling pathways that favor cancer cell survival and proliferation, EGF and its receptor EGFR, along with key downstream effectors such as PKB and GSK-3β." (PMID 40656954, 2025). "EGF is involved in the metabolism and transport of a range of amino acids across many cancer models." (PMID 39433211, 2025). "Growth factors like TGF‐β, IGF, EGF, and FGF are ARs dependent, and EGF, with its membrane‐related tyrosine receptor kinase EGF‐1, is responsible for the progress of cancer cells by enhanced migration." (PMID 40761498, 2025). "Studies have shown that cancer cells can induce epithelial-mesenchymal transition in normal epithelial cells by secreting transforming growth factor-β and epidermal growth factor, increasing cell migration and invasion capabilities." (PMID 40666516, 2025). "Analysis of PDP1 expression in pan-cancer found that PDP1 is widely expressed in epidermal growth factor-activated cells and various human malignant tumor cells." (PMID 40746885, 2025). "While EGF influences glucose metabolism in a diverse range of cell types, its effects are particularly well studied in cancer models." (PMID 39433211, 2025). "The CIMAvax-EGF is a therapeutic vaccine developed in Cuba, designed to block the action of the epidermal growth factor (EGF), a protein that plays a critical role in the growth and proliferation of cancer cells." (PMID 41303538, 2025). "We stimulated control and CMTM4 KD cells with EGF and found that the control cancer cells secreted a high level of G-CSF, while CMTM4 KD cells significantly reduced G-CSF production." (PMID 39948411, 2025). "Several growth factors like TGF‐β, IGF, EGF, and FGF are ARs dependent, and EGF, with its membrane‐related tyrosine receptor kinase EGF‐1, is responsible for the progression of cancer cells by enhancing migration." (PMID 40755497, 2025). "CIMAvax‐EGF is a therapeutic cancer vaccine composed of a human recombinant EGF‐binding carrier protein and Montanide ISA51 as an adjuvant." (PMID 40859900, 2025). "CIMAvax-EGF is a molecular cancer vaccine that induces an immune response against circulating the epidermal growth factor (EGF) ligand." (PMID 40001556, 2025). "Specifically, the vaccine stimulates a B-cell response to produce antibodies that bind to and neutralize EGF in the body, preventing it from interacting with receptors on the surface of cancer cells." (PMID 40872964, 2025). "Cancer-related markers expressed in this line include epidermal growth factor (EGF) and transforming growth factor beta (TGF-β) (“ATCC Human Cells MDA”, [Online]." (PMID 41304905, 2025).
cancer (continued). "We have designed the experiment to treat SKBR3 cancer cells with EGF (100 ng/mL) and observe the kinetic time course of protein–protein complex formation." (PMID 39789599, 2025). "To test the functionality of our site‐specifically labeled EGF constructs, we used the human cancer cell line A549, stably expressing EGFR‐GFP." (PMID 40181613, 2025). "Research data show that the EGF gene and its receptor gene EGFR are closely associated with cancer occurrence and metastasis." (PMID 40696566, 2025). "Increasing evidence has revealed that many factors secreted and produced by TAMs enhance cancer progression, such as EGF, PDGF, CXCL8, MMP9, and FGF2 in the TME." (PMID 40076874, 2025). "Our previous work revealed that EGF elicits cancer metastasis and ACAP4 orchestrates EGF-elicited cellular dynamics." (PMID 40082743, 2025). "Various signaling pathways, like PI3K/AKT/mTOR and EGF/RAS/RAF/MEK/ERK, are pivotal in oncogenesis, associated with cancer progression and drug resistance in different types of human cancer." (PMID 40806663, 2025). "Epidermal growth factor (EGF) is one of the most studied growth factors involved in cancer cell chemotaxis." (PMID 38426123, 2024). "When this pathway is activated by the phosphorylation of Akt, in response to various growth factors such as vascular endothelial growth factor (VEGF) or epidermal growth factor (EGF), it can induce metastasis and chemoresistance in several types of cancer." (PMID 38473317, 2024). "Among the main growth factors involved in the development of cancer which represent important therapeutic targets, are the Epidermal Growth Factor (EGF) and the Vascular Endothelial Growth Factor (VEGF)." (PMID 38636197, 2024). "The first-named cytokine promotes macrophage movement and stimulates EGF secretion, which in turn sends messages to the cancer cells and facilitates chemotactic migration in the direction of the blood vessels." (PMID 38397421, 2024). "We have identified potent, metabolically stable Gαi2 inhibitors, which we validated as novel inhibitors of intrinsic and EGF-stimulated migration of cancer cells." (PMID 38254786, 2024). "This paracrine cycle between macrophages and cancer cells is mediated by EGF, and CSF-1 promotes tumor invasion." (PMID 38787372, 2024). "When inserting the adapter A2 between the RIP saporin and the targeting moiety EGF (Saporin-A2-EGF), an improved anti-cancer effect in mice with EGFR-positive tumors and simultaneously lesser side effects were observed in comparison to Saporin-EGF." (PMID 38685061, 2024). "On the other hand, TAMs channel cancer cells into the bloodstream through a positive feedback circuit comprising CSF-1 secreted by the cancer cells and EGF secreted by TAMs." (PMID 38397421, 2024). "TAM-derived EGF activated EGFR on cancer cells, then increases expression of VEGF-C and VEGFR3 in cancer cells." (PMID 39513610, 2024). "The association between these three genes, EGF, EPHB3, and POTEF, and Run Variance indicates their roles in the heterogeneous colonization of cancer cells." (PMID 38811597, 2024). "IL-6 has also been reported to regulate cancer cell proliferation through the epidermal growth factor (EGF) and hepatocyte growth factor (HGF) families." (PMID 38510850, 2024). "The combination with the clinical approved monoclonal antibody anti-epidermal growth factor EGFR Cetuximab (Cetuximab-IRDye800) has shown promising results as a specific tracker in different cancer types (i.e., brain, pancreas, head, and neck)." (PMID 39218855, 2024). "Recently, several antagonists that inhibit Hh, PDGF, EGF and Wnt signalling have become available for cancer treatment." (PMID 39234399, 2024). "Intriguingly, recent work similarly identified Piezo1 as a regulator of epidermal growth factor-stimulated macropinocytosis in cancer cells." (PMID 38265917, 2024).
cancer (continued). "Our results showed that control and DOCK4-depleted cancer cells almost double their filopodia in response to EGF treatment, whereas upon TGFβ stimulation, the number of filopodia remained unchanged in both control and DOCK4-depleted cells." (PMID 38762624, 2024). "Both EGFR mutations and EGF/EGFR hypo‐methylation activated the EGFR pathway, fueling cancer growth." (PMID 39036344, 2024). "Using these cells, we conducted anchorage-independent cell transformation and cancer cell colony growth assays induced by EGF or basic fibroblast growth factor (bFGF)." (PMID 39424777, 2024). "Our previous results demonstrated that RSK2 plays a key role in cell transformation induced by growth factors, such as EGF and bFGF, and cancer cell proliferation." (PMID 39424777, 2024). "Epidermal growth factor (EGF) serves as a basis for a large family of peptide ligands that govern cancer cell growth, proliferation, and angiogenesis by binding to cell membrane receptors and activating a broad range of intracellular signalling pathways." (PMID 39512829, 2024). "The IRDye800 conjugated with the clinically approved monoclonal antibody anti-epidermal growth factor EGFR Cetuximab (cetuximab-IRDye800) has shown promising results as a specific tracker in other cancer types (i.e., brain, pancreas, head, and neck)." (PMID 39218855, 2024). "Here, cytoplasmic and nuclear EGF expression was observed, with a predominance of protein in the cytoplasm of malignant tumors." (PMID 38636197, 2024). "The image captured by confocal microscopy demonstrated that CGN c.3560C > T leads to reorganized F-actin network from cortical thin bundles into thick contractile stress fibers in cancer cells after EGF treatment." (PMID 38424547, 2024). "For instance, curcumin encapsulated in epidermal growth factor (EGF) conjugated chitosan nanoparticle (CENP) was shown to exhibit promising anticancer effects against EGF receptor overexpressing cancer cells." (PMID 38543316, 2024). "More importantly, PL has been shown to reduce cancer growth by affecting the epidermal growth factor pathway." (PMID 38635559, 2024). "The EGF signaling pathway overactivation is strongly involved in cancer progression and is often targeted during anti-cancer treatment." (PMID 38495105, 2024). "PAX1 activated a group of phosphatases, including DUSP1, 5, and 6, and inhibited EGF/MAPK signaling to suppress cancer development." (PMID 39304838, 2024). "We produced novel superantigen SEA-peptide agonists and SEA-peptide-agonist–EGF conjugates for the targeted treatment of EGFR-expressing cancers." (PMID 39273378, 2024). "Transforming growth factor beta (TGF-β), fibroblast growth factor 2, platelet-derived growth factor, and epidermal growth factor (EGF) are secreted not only by stromal cells but also by cancer cells." (PMID 38542199, 2024). "Most recently, we reported that stabilin-1 mediates the clearance of the most potent growth factor that supports the proliferation of cancer cells, EGF." (PMID 39516356, 2024). "EGFR, a member of the ErbB receptor family, orchestrates extracellular signals, such as EGF, directing cellular signaling cascades to promote cell proliferation, division, mitosis, and cancer development." (PMID 38817007, 2024). "Cancer cells recruit TAMs by secreting colony-stimulating factor-1, and in return, TAMs facilitate cancer cell growth by producing EGF." (PMID 38254110, 2024). "The interaction between EGF and EGFR is a key molecular mechanism that contributes to cell growth and survival, and dysregulation of this pathway is often associated with cancer development and progression." (PMID 38343537, 2024). "PDP1 is widely expressed in epidermal growth factor activated cells and various malignant human cancer cells." (PMID 38198170, 2024). "TAMs have been found to release EGF and travel in streams together with cancer cells in the direction of blood vessels." (PMID 38397421, 2024).
cancer (continued). "During the metastasis, TAMs and cancer cells develop a symbiotic relationship by releasing the epidermal growth factor (EGF) and colony-stimulating factor 1 (CSF-1), respectively." (PMID 38361941, 2024). "TAMs have been found to express multiple cytokines, such as epidermal growth factor, platelet‐derived growth factor, and transforming growth factor‐β, which promote the proliferation and migration of cancer cells." (PMID 39548034, 2024). "These cells are able to secrete their own EGF, which, combined with the lower demand for this polypeptide, makes cancer cells proliferate and multiply more quickly." (PMID 38338748, 2024). "Throughout cancer progression, the T-BOX family has been found to be closely associated with key oncogenic pathways such as NF-kB, WNT/β-catenin, EGF\EGFR." (PMID 38965548, 2024). "Both are involved in the regulation of several pathways to promote cancer progression as cell proliferation, metastasis, and angiogenesis by binding a large variety of ligands including epidermal growth factor (EGF) and transforming growth factor-α (TGFα)." (PMID 39199659, 2024). "EGFR is associated with cell survival, differentiation, and proliferation as it binds to its ligand, EGF, whose structural activation promotes various human cancers metastasizing." (PMID 38965548, 2024). "One study examined immunosenescence biomarkers, highlighting that senior NSCLC patients with higher frequencies of specific T cell populations had better responses to the CIMAvax-EGF cancer vaccine." (PMID 39195131, 2024). "Recently, EGF signals were found to be highly associated with alternative splicing and APA processes in cancers and other developmental diseases, especially for their role in 3’UTR shortening." (PMID 38418967, 2024). "Long since, the epidermal growth factor (EGF) receptor (EGFR) has thus been targeted in specific treatments of various cancer types." (PMID 38685061, 2024). "Further, SELENOW is expressed in the brain and is implicated in EGF signaling and redox regulation, while TIMM8A is involved in mitochondrial function with its role in cancer currently evolving." (PMID 39123468, 2024). "Studies have examined the effect of PS-NPs on epidermal growth factor (EGF) in the human epithelial carcinoma cell line A431." (PMID 38727304, 2024). "One of the key factors is the high expression of epidermal growth factor (EGF) in TAMs, which activates epidermal growth factor receptors (EGFRs) in cancer cells, leading to metastasis and increased secretion of colony-stimulating factor 1 (CSF-1)." (PMID 37445965, 2023). "Neutrophils also play a role in promoting cancer growth by releasing growth factors, including epidermal growth factor, hepatocyte growth factor (HGF), and platelet-derived growth factor." (PMID 37894307, 2023). "This stress influences the activities of matrix metalloproteinases, adhesion molecules, and the epidermal growth factor and its receptor, which are instrumental in cancer progression and metastasis." (PMID 38067221, 2023). "Strikingly, despite the proven potential of EGF as a cancer target, there are very few investigations focused on EGF immunotargeting." (PMID 37241784, 2023). "Since Sorcin is overexpressed in different types of tumors and is involved in the calcium-linked regulation of pathways triggered by EGFR, we investigated the role of Sorcin in EGF-dependent invasion of cancer cells." (PMID 37442828, 2023). "Similar to other devices for probing spontaneous cancer cell migration, the devices employed in this study rely on self-generated gradients of epidermal growth factor (EGF)." (PMID 38155198, 2023). "Cancer progression, however, is sustained by signals and paracrine loops, involving, for example, gradients of epidermal growth factor and colony-stimulating factor that activate tumor stromal cells (cancer-associated fibroblasts; CAFs) in the vicinity." (PMID 37627015, 2023).